CD55 (CD55 molecule (Cromer blood group))
Description:
This protein recognizes C4b and C3b fragments that condense with cell-surface hydroxyl or amino groups when nascent C4b and C3b are locally generated during C4 and c3 activation. Interaction of daf with cell-associated C4b and C3b polypeptides interferes with their ability to catalyze the conversion of C2 and factor B to enzymatically active C2a and Bb and thereby prevents the formation of C4b2a and C3bBb, the amplification convertases of the complement cascade. Inhibits complement activation by destabilizing and preventing the formation of C3 and C5 convertases, which prevents complement damage. (Microbial infection) Acts as a receptor for Coxsackievirus A21, coxsackieviruses B1, B3 and B5. (Microbial infection) Acts as a receptor for Human enterovirus 70 and D68 (Probable). (Microbial infection) Acts as a receptor for Human echoviruses 6, 7, 11, 12, 20 and 21.
Synonyms: CR; DAF; TC; CROM; CHAPLE
Tractability: Small molecule: a structure with a bound ligand is known; it has a binding pocket of medium quality. Antibody: UniProt places it where antibodies can reach, with high confidence; its Gene Ontology location is reachable by antibodies, with high confidence; UniProt predicts a signal peptide or a membrane-spanning region. PROTAC: ubiquitination databases record sites on it; its protein half-life has been measured.
Gene: Protein-coding gene on chromosome 1 (207,321,514 to 207,386,804, forward strand). Ensembl gene ENSG00000196352.
Subcellular location: Cell membrane (Isoform 1); Cell membrane (Isoform 2); Secreted (Isoform 3); Secreted (Isoform 4); Secreted (Isoform 5); Cell membrane (Isoform 6); Cell membrane (Isoform 7)
Pathways (Reactome):
Immune System: Neutrophil degranulation; Regulation of Complement cascade
Signal Transduction: Class B/2 (Secretin family receptors)
Vesicle-mediated transport: COPI-mediated anterograde transport
Gene Ontology:
Molecular function: lipid binding; protein binding; virus receptor activity
Biological process: negative regulation of complement activation; positive regulation of CD4-positive, alpha-beta T cell activation; positive regulation of CD4-positive, alpha-beta T cell proliferation; positive regulation of cytosolic calcium ion concentration; positive regulation of T cell cytokine production; regulation of complement activation; regulation of complement-dependent cytotoxicity; regulation of lipopolysaccharide-mediated signaling pathway; respiratory burst; regulation of adaptive immune response based on somatic recombination of immune receptors built from immunoglobulin superfamily domains; regulation of lymphocyte mediated immunity; symbiont entry into host cell
Cellular component: cell surface; extracellular exosome; membrane raft; plasma membrane; endoplasmic reticulum-Golgi intermediate compartment membrane; extracellular region; ficolin-1-rich granule membrane; Golgi membrane; secretory granule membrane; transport vesicle
Genetic constraint (gnomAD): Loss-of-function variants: 20 observed, 23.56 expected, observed/expected ratio (o/e) 0.85, 90% interval 0.6 to 1.23. The upper end of that interval is the gene's LOEUF score, 1.23, which puts it in group 5 of 6, group 1 being the genes least tolerant of losing a copy. Missense variants: 295 observed, 310.53 expected, observed/expected ratio (o/e) 0.95, 90% interval 0.86 to 1.05. Synonymous variants: 136 observed, 123.36 expected, observed/expected ratio (o/e) 1.1, 90% interval 0.96 to 1.27.
Homologues: Orthologues: chimpanzee CD55 (98% identical), macaque CD55 (73% identical), dog CD55 (54% identical), mouse Cd55 (49% identical), rat Cd55 (48% identical), pig CD55 (46% identical), guinea pig Cd55 (45% identical), mouse Cd55b (44% identical). Paralogues in human: CR1 (27% identical), CSMD1 (25% identical), CSMD3 (24% identical), CR2 (23% identical), C4BPA (22% identical), CSMD2 (22% identical), SVEP1 (21% identical), CR1L (20% identical), CD46 (19% identical), CFH (17% identical), SEZ6L (17% identical), SEZ6L2 (17% identical), and 27 more.
Diseases named in the same sentence as CD55 in open-access papers:
CD55 is named in the same sentence as 239 diseases in open-access papers, as found by Europe PMC text mining. Sharing a sentence is not in itself a finding about the gene and the disease. The quoted sentences say what the papers report.
paroxysmal nocturnal hemoglobinuria (52 papers, 2009 to 2026). Paroxysmal nocturnal hemoglobinuria (PNH) is an acquired clonal hematopoietic stem cell disorder characterized by corpuscular hemolytic anemia, bone marrow failure and frequent thrombotic events. "The spectrum of clinical presentations associated with complement dysregulation also includes protein-losing enteropathy (CD55 deficiency) and paroxysmal nocturnal hemoglobinuria (PNH) (CD55+CD59 deficiency)." (PMID 34434189, 2021). "These include angioedema (C1 inhibitor [C1-INH] deficiency), kidney and eye diseases (FH, FI or CD46 deficiency), protein-losing enteropathy (CD55 deficiency) and paroxysmal nocturnal hemoglobinuria (PNH) (CD55 + CD59 deficiency)." (PMID 32064578, 2020). "It is also known that a deficiency of CD55 leads to the development of paroxysmal nocturnal hemoglobinuria." (PMID 26928779, 2016). "In the context of acquired BMF syndromes, paroxysmal nocturnal hemoglobinuria (PNH) is a clonal disease caused by a somatic mutation in the PIGA-gene resulting in the deficiency of GPI-anchored proteins (such as CD55 and CD59) and leads to erythrocytes unable to control complement activation." (PMID 36439498, 2022). "Paroxysmal nocturnal hemoglobinuria (PNH) is a hematological disorder caused by a deficiency in glycosylphosphatidylinositol anchor synthesis that negatively affects the expression of the CRPs CD55 and CD59." (PMID 34359708, 2021). "This C5 inhibitor has been evaluated for paroxysmal nocturnal hemoglobinuria (PNH), CD55-deficient protein-losing enteropathy, and CHAPLE disease." (PMID 38140161, 2023). "Conversely, in patients with paroxysmal nocturnal hemoglobinuria, where CD59 (and CD55) are deficient, RBCs become highly susceptible to intravascular hemolysis." (PMID 41431006, 2025). "For instance, deficiency in complement regulators CD55 and CD59, leads to paroxysmal nocturnal hemoglobinuria (PNH), whereas Factor H mutations predispose to atypical hemolytic uremic syndrome (aHUS), both causing severe thrombohemolysis." (PMID 32793201, 2020). "Somatic PIGA mutations cause paroxysmal nocturnal hemoglobinuria (PNH) (MIM 300818), an acquired complement‐mediated hemolytic disease resulted from loss of GPI‐anchored CD55 and CD59 on erythrocytes." (PMID 29974678, 2018). "After exclusion of Fanconi anemia (no spontaneous and diepoxybutane‐induced chromosome breakage) and paroxysmal nocturnal hemoglobinuria (normal CD55/CD59 expression in granulocytes and erythrocytes), a diagnosis of idiopathic aplastic anemia was made." (PMID 29191945, 2018). "Mutations in another enzyme in the GPI synthesis pathway, PIGA, cause paroxysmal nocturnal hemoglobinuria, in which hematopoietic stem cells produce RBCs lacking CD55 and CD59, 2 surface proteins that prevent RBCs hemolysis." (PMID 41431006, 2025). "ECU can effectively prevent hemolysis in paroxysmal nocturnal hemoglobinuria (PNH) caused by a lack of complement-regulating CD55 and CD59 on blood cells." (PMID 24086391, 2013). "Flow cytometry confirmed a deficiency of CD55 and CD59, diagnostic of paroxysmal nocturnal hemoglobinuria (PNH)." (PMID 41450399, 2025). "Paroxysmal nocturnal hemoglobinuria (PNH) is a rare, acquired clonal hematologic disorder caused by somatic mutations in the PIGA gene of hematopoietic stem cells, leading to the absence of GPI-anchored proteins, including the complement regulators CD55 and CD59." (PMID 41002734, 2025). "Patients with paroxysmal nocturnal hemoglobinuria (PNH) have defective complement regulators, CD55 and CD59, and an increased incidence of adverse pregnancy outcomes." (PMID 32849586, 2020). "RBCs of patients with paroxysmal nocturnal hemoglobinuria (PNH) lack the GPI-anchored proteins CD55 and CD59 that protect against complement activation-associated hemolysis." (PMID 29937736, 2018).
paroxysmal nocturnal hemoglobinuria (continued). "Paroxysmal nocturnal hemoglobinuria (PNH) is a rare, X-linked blood disorder in which red blood cells lack the GPI-APs CD55 and CD59 due to somatic mutations in a gene (phosphatidylinositol glycan class A, PIGA)." (PMID 28785375, 2017). "FCM analysis performed on peripheral blood demonstrated CD55(−) CD59(−) granulocytes (approximately 42%) and red blood cells (approximately 16%), consistent with paroxysmal nocturnal hemoglobinuria (PNH)." (PMID 39910008, 2025). "Our group generated disease-free iPSCs from the fibroblasts of a patient with paroxysmal nocturnal hemoglobinuria (PNH), whose granulocytes and red blood cells consist of a minor normal population and major population with decreased surface CD55 and CD59." (PMID 34831472, 2021). "Defects in the biosynthesis of GPI causes paroxysmal nocturnal hemoglobinuria (PNH), a hematological disease characterized by increased intravascular hemolysis and complement activation due to the absence of CD55 and CD59." (PMID 31417415, 2019). "This treatment was initially registered for patients with paroxysmal nocturnal hemoglobinuria (PNH), where an acquired defect in the glycophosphoinositol-anchored natural complement inhibitors, CD55 and CD59 leads to complement-mediated hemolysis." (PMID 25688346, 2015). "Paroxysmal nocturnal hemoglobinuria (PNH) is a disease that involves hemolysis caused by the lack of CD55- or CD59-mediated complement activity inhibition in the absence of GPI anchor on the surface of red blood cells." (PMID 24455465, 2014). "This is the case in paroxysmal nocturnal hemoglobinuria (PNH), where a proportion of bone marrow-derived cells lack GPI-anchored CD59 and CD55." (PMID 24119446, 2013). "Paroxysmal nocturnal hemoglobinuria (PNH) is a rare, chronic, and potentially life-threatening hematological disorder caused by genetic mutations that lead to the absence of complement regulatory proteins CD55 and CD59 on red blood cells." (PMID 40430547, 2025). "In paroxysmal nocturnal hemoglobinuria (PNH), acquired mutations in the phosphatidylinositol glycan class A gene on hematopoietic stem cells lead to a loss of CD55 and CD59, important negative complement regulators on red cell membranes." (PMID 40338657, 2025). "In fact, downregulation or lack of CD55 and CD59 expression is associated with clinical diseases including paroxysmal nocturnal hemoglobinuria and dysferlin-deficient muscular dystrophy." (PMID 25254972, 2014). "CD55 and CD59 were expressed normally on erythrocyte, granulocyte and monocyte, which excluded the diagnosis of paroxysmal nocturnal hemoglobinuria (PNH)." (PMID 41472573, 2026). "Paroxysmal nocturnal hemoglobinuria (PNH) is a rare and progressive hematopoietic stem cell disorder in which hematopoietic cells are deficient in glycosylphosphatidylinositol (GPI), which leads to a lack of the complement inhibitor proteins CD55 and CD59 on the surface of blood cells." (PMID 24587926, 2014). "Assessment of peripheral blood flow cytometry for CD55 and CD59 was negative, which excludes paroxysmal nocturnal hemoglobinuria (PNH)." (PMID 40703529, 2025). "ECU is a monoclonal anti-C5 antibody which inhibits C5 activation, thus blocks the terminal pathway of the complement system irrespective of lacking CD55 and CD59 on peripheral blood cells and is most effective in paroxysmal nocturnal hemoglobinuria (PNH)." (PMID 24086391, 2013). "Immunophenotyping in the peripheral blood revealed normal CD55 and CD59 expression and paroxysmal nocturnal hemoglobinuria (PNH) was not considered." (PMID 20062604, 2009). "Consequently, the autoimmune antibody, fluorescently labeled modified aerolysin (FLAER), CD55\CD59 expression, and direct antiglobulin (Coombs) tests were not abnormal, which ruled out paroxysmal nocturnal hemoglobinuria (PNH) and autoimmune hemolytic anemia." (PMID 33592896, 2021).
breast carcinoma (29 papers, 2005 to 2025). "Lin and colleagues recently demonstrated that ST3GAL1-mediated O-linked sialylation of CD55, an important complement regulatory protein, acts like an immune checkpoint molecule for breast cancer cells to evade immune attack." (PMID 33921986, 2021). "CD55 overexpression was also reported as an independent risk factor for recurrence of breast cancer in patients receiving postoperative adjuvant therapy containing trastuzumab." (PMID 31024572, 2019). "When accounting for overall cell number, the relative surface expression level of CD59 and CD55 was observed to increase appreciably in glutamine-restored breast cancer cells, which explains the associated increased complement resistance." (PMID 17623109, 2007). "HNRNPU is a splicing factor which recently has been implicated in APA of CD55 in breast cancers." (PMID 39188787, 2024). "Similarly, in breast cancer, high CD55 expression in patient tumors is associated with lower relapse-free survival." (PMID 38612911, 2024). "Mechanistically, authors showed that O-linked desialylation of CD55 by ST3GAL1 silencing results in increased C3 deposition and complement-mediated lysis of breast cancer cells, enhancing sensitivity to antibody-dependent cell-mediated cytotoxicity." (PMID 33921986, 2021). "Neutralization of CD55 in Burkitt lymphoma cells, leukemia cells, melanoma cells, and breast cancer cells increased their sensitivity to complement." (PMID 31024572, 2019). "For example, neutralization of CD55 has led to increased complement activation and complement-mediated killing in Burkitt lymphpoma, leukemia, melanoma, and breast cancer." (PMID 31164885, 2019). "In the setting of breast cancer, it was found that cells expressing high CD55 levels were more resistant to apoptotic stimuli, have a higher growth rate, and in human cancer, are an independent prognostic factor for recurrence." (PMID 31164885, 2019). "From the gene coexpression network of BRCA, we see some breast cancer associated genes are isolated, such as ‘TNF’, ‘CD55’, ‘IL1A’." (PMID 29671401, 2018). "CD55 play an important role in tumorigenesis of breast cancer, and presence of small population of cells with strong CD55 expression would be sufficient to predict poor prognosis in patients." (PMID 22634835, 2012). "CD55 was also found expressed on side-population (SP) cells of mammary carcinoma cell lines and used for isolation of cancer stem cells." (PMID 20175889, 2010). "A protein involved in innate immune response which is critical to the regulation of the complement cascade, CD55, has been shown to be important in prostate growth, gastric tumor invasiveness and breast cancer prognosis." (PMID 19208118, 2009). "Coincidently, the rapidly proliferating glutamine-restored breast cancer cells demonstrated increased complement resistance in association with the increased expression of CD59 and CD55." (PMID 17623109, 2007). "Nonetheless, increased CD59 and CD55 expression protect breast cancer cells form antibody-directed complement activation." (PMID 17623109, 2007). "Furthermore, xenotransplantation of CD55+ MCF-7 breast cancer cells into NOD/SCID mice resulted in significantly increased tumor volume compared to tumors derived from a CD55low population." (PMID 38612911, 2024). "Altered CD55 expression has been identified as a significant biomarker in breast cancer." (PMID 36694725, 2023). "We previously reported that CD55 expression is higher in metastatic versus primary breast cancers and may contribute to the immune attenuated microenvironment of metastatic lesions." (PMID 35869114, 2022). "In addition, neutralization of CD55 has led to increased complement activation and complement-mediated killing in breast cancer, melanoma, Burkitt lymphoma, and leukemia." (PMID 33614473, 2020).
breast carcinoma (continued). "Furthermore, identified six genes (TSPYL5, CD55, CCNE2, DCK, BBC3, and MUC1) susceptible to breast cancer were verified through the literature mining, GO analysis, and pathway functional enrichment analysis." (PMID 24073403, 2013). "Among these oncogenes, TSPYL5 and CCNE2 have been already known as prognostic biomarkers in breast cancer, CD55 has been suspected of playing an important role in breast cancer prognosis from literature evidence, and other three genes are newly discovered breast cancer biomarkers." (PMID 24073403, 2013). "CD55 has been shown to be important in breast cancer prognosis." (PMID 24073403, 2013). "In many tumor types (lung cancer, breast cancer, pancreatic cancer, kidney cancer), complement proteins C1q, C1s, C3, C4, anaphylatoxins C3a and C5a and their receptors and regulatory proteins (such as factor B, factor H, factor I, CD55 and CD59) are most often overexpressed." (PMID 40596619, 2025). "Similarly, the elevated levels of ICAM-1 (Intercellular Adhesion Molecule – 1) and decay-accelerating factor (DAF/CD55) in cancers like breast cancer, multiple myeloma, and melanoma allow coxsackievirus (e.g., coxsackievirus A21) to induce oncolysis within these malignancies." (PMID 41313526, 2025). "EPCAM and KRT18 were employed to label epithelial cells, whereas ALDH2, CD55, and ALDH6A1 were used to identify breast cancer stem cells." (PMID 40092692, 2025). "Lipoplex-mediated delivery of siRNAs against CD55, CD46, and CD59 sensitized breast cancer BT474 and SKBR3, ovarian cancer SKOV3, and lung cancer Calu-3 cells to trastuzumab and pertuzumab." (PMID 38612911, 2024). "For example, CD46, CD55, and CD59 were reported to be up-regulated through p-ERK1/2/NF-κB signaling to protect breast cancer from CDC." (PMID 33614473, 2020). "CD55 and CD59 expression were also correlated with the protection of HER2-overexpressing breast cancer and uterine serous carcinoma cells from trastuzumab-induced complement dependent cytotoxicity." (PMID 31164885, 2019). "In contrast, levamisole reduces CD59 levels in colon adenocarcinoma cell lines and after pretreatment of breast carcinoma cells with tamoxifen, trastuzumab-induced CDC was enhanced due to CD55 down-regulation." (PMID 31024572, 2019). "Using netSAM, we identified six novel genes (TSPYL5, CD55, CCNE2, DCK, BBC3, and MUC1) as cancer biomarkers for predicting survival and metastasis in patients with breast cancer." (PMID 24073403, 2013). "Recent researches about Hepatitis B X-interacting protein (HBXIP) function on the breast cancer cells has been shown that CD55, CD59, and CD46 are up-regulated through p-ERK1/2/NF-jB signaling to protect breast cancer from complement-dependent cytotoxicity." (PMID 22634835, 2012). "Similarly, breast carcinoma cells were more easily lysed after treatment with anti-CD59 and anti-CD55 antibodies, but a much higher degree of lysis was achieved when a mixture of anti-CD59, anti-CD55, and anti-CD46 antibodies was used." (PMID 35227072, 2022). "Recently, PET-based detection and monitoring of metastasis cancer has utilized the following antibodies: 111In-labeled anti-CDH17 (gastric cancer), 177Lu-labeled anti-CD55 (lung cancer), and radio-labeled anti-ERBB2 (various labeling, including 89Zr, 64Cu, 111In) (breast cancer)." (PMID 34680307, 2021). "Previous studies show that the expression level of the CD55 gene is greater in individuals with gastric, colon, and breast cancer, than in non-cancerous tissues, and the expression was higher in Yunnan humped cattle compared to Holstein cattle." (PMID 31387199, 2019). "Silencing of CD55 and CD59 in breast cancer cells with specific shRNA enhanced CDC." (PMID 31024572, 2019).